IL10 (interleukin 10)
Diseases named in the same sentence as IL10 in open-access papers (continued):
Sharing a sentence is not in itself a finding about the gene and the disease.
infection (continued). "In this study, we found that IL-10 reduced the extent of apoptosis of uninfected cells in the vicinity of T. gondii infected cells at early infection stage (24 hr), but the detailed mechanisms involved as well as the effects on pregnancy of infected mice deserve further investigation." (PMID 23418570, 2013). "This pathway may be more important at later stages of the infection once antibody responses have developed, which may explain the low level of IL-10 produced by myeloid cells at 1 week of infection." (PMID 23555256, 2013). "Interestingly, sera IL-10 levels in WNV H8912-infected mice were constitutively high within the first two weeks of infection." (PMID 23785537, 2013). "Notably, the lack of IL-10 significantly increased the frequency of IFN-γ+ CD8+ and CD4+ T cells in the lung on day 8 post infection, supporting the conclusion that IL-10 is important for dampening the activation of inflammatory T cells during RSV infection." (PMID 22393401, 2012). "Thus, the 2-day infection time-point was chosen to test the anti-inflammatory effect of IL-10 on the production levels of cytokines as induced by C. trachomatis-infected HeLa and J774 cells." (PMID 22529524, 2012). "The BT group showed a decrease in the percentage of cells CD4+IL-10+ at day 7 after infection, however higher levels of IL-10+ T-cells were seen in both groups, but this level increased at day 28 in MT group, an effects seen this increase occurred earlier at day 14 in the BT group." (PMID 22412949, 2012). "The production of IL-4, IL-5, IL-6, and IL-10, which in turn promote B-cell proliferation and antibody production, is the cause of susceptibility of dogs, which become not able to control the infection." (PMID 22400039, 2012). "The asymptomatic nature of the infections in our pregnant women could, thus, reflect the suppressive effects of increased amounts of IL-10." (PMID 23155405, 2012). "T cells expressed negligible amounts of IL-10 or IFN-γ in the lung and bronchoalveolar lavage fluid (BAL) on day 4 post RSV infection (not depicted), but both CD4+ and CD8+ T cells from the lung or airways frequently expressed IFN-γ and IL-10 on day 8 post infection." (PMID 22393401, 2012). "Notably, it has been demonstrated thathost-protective IL-10 is produced, through autocrine signaling, by conventionalIFN-γ-producing Th1 cells during infection with Toxoplasma gondii." (PMID 22802961, 2012). "Recent studies have shown IL-10 expression by macrophages in response to bacterial lipopolysaccharide (LPS) is p38-dependent, but this is the first description of p38-dependent IL-10 expression in the context of infection and attributed to bacterial virulence." (PMID 22829768, 2012). "On day 4 after infection, we found that higher frequencies of IL-10/GFP+ cells were NK1.1+ TCRβ− (NK cells), as compared to NK1.1+ TCRβ+, NK1.1− TCRβ−, and NK1.1− TCRβ+ cells (NK cells 56%±3% compared to NK1.1+ T cells: 5%±1%, and non-NK non T cells: 12%±1%, and T cells: 27%±2%)." (PMID 22880122, 2012). "Upon infection, IL-10 can be secreted by many different cell types." (PMID 22876184, 2012). "In accordance to previous studies, which showed that IL-10 would play an important role in regulating the strong Th1 response elicited by T. gondii, IL-10-deficient mice showed increased mortality during the acute phase of infection (data not shown)." (PMID 22952678, 2012). "In addition, IL-10 has been demonstrated to inhibit osteoclast differentiation in vitro and to suppress infection-induced bone resorption in a murine model of periodontitis." (PMID 22507741, 2012). "Indeed, IL-10 levels in the serum of infected mice were detectable early upon infection, reaching a peak at day 5 p.i.." (PMID 22876184, 2012).
infection (continued). "In RAG−/− mice that had been infected with H. polygyrus, and subsequently drug-cleared of the infection prior to transfer of the colitogenic IL-10−/− T cells and piroxicam administration, mice still showed reduced levels of inflammation compared to those that had never been infected." (PMID 23053394, 2012). "Therefore, our results highlight the role for IL-10 and cellular sources of IL-10 in the protection of the liver from damage due to infection induced inflammatory responses." (PMID 22880122, 2012). "However, it has also been shown that IL-10 expression varies with infection using different strains of the PRRSV; thus, it is unclear if Treg-mediated suppression of immune response occurs with all the strains of PRRSV." (PMID 22340040, 2012). "WT mice produced more IFNγ and IL-10 mRNA at the infection site 2 weeks after L. major infection." (PMID 22007288, 2012). "Our IL-10 results indicate a T regulatory activity in patients with active TB; still higher levels could possibly have been found at the site of infection compared with peripheral blood." (PMID 23144772, 2012). "However, IL-10-deficient mice had increased total cell numbers in the lung and BAL on day 8 post RSV infection while total cell numbers in the BAL on day 4 post infection were decreased in IL-10−/− mice compared to controls." (PMID 22393401, 2012). "Moreover, the ratio of TGF-β1/TNF-α and of IL-10/TNF-α production were higher in DCL than LCL isolates at 24 h post-infection." (PMID 22574191, 2012). "Although IL-10 may be extracted from murine spleen cells after 1 day of infection, the levels of this cytokine are far lower than those induced by other bacteria." (PMID 22500859, 2012). "Furthermore, decreased IL-10 expression upon infection with 10/84ΔcylE bacteria correlated with increased IL-12p40 and NOS2 mRNA." (PMID 22829768, 2012). "Several parasites also induce IL-10 production, probably to allow persistence of infection." (PMID 22393401, 2012). "The levels of TNFα and IL10 were too low to be detectable at this dose of infection." (PMID 22719255, 2012). "Therefore, O. tsutsugamushi activates both proinflammatory and modulatory pathways, via IL-10, in the early stages of infection." (PMID 21912565, 2012). "Therefore, BALB/c WT or IL-10−/− mice were infected with RSV; mice were monitored for disease and daily weight loss and lung/BAL cells analyzed on day 4 and 8 post infection." (PMID 22393401, 2012). "When compared with plasma samples from an independent cohort of healthy individuals, cytokines IP-10, VEGF and PDGF-BB were found to be elevated >20 times over controls during the febrile phase of infection, while IL-4, IL-9, IL-10 and IL-1ra were elevated by 10–20 times over controls." (PMID 23209847, 2012). "In addition, high levels of IL-10 were detected in the serum of mice after infection with B. microti." (PMID 23071588, 2012). "Similarly, mRNA levels for CD3, TNF-α, IFN-γ, iNOS, IL-10 and arginase I declined in WT spinal cords about the fourth or fifth week after infection, but kept increasing in IL-12p40KO mice." (PMID 23152844, 2012). "B cells from patients with infections from other parasites such as Trypanosoma cruzi exhibit IL-10 levels similar to those in uninfected MS patients, indicating that intracellular parasites are unable to down-modulate harmful autoimmune responses in the way helminths do." (PMID 22937527, 2012). "Tracking the gene expression profile of target inflammatory genes, we observed that in WT spinal cords the amount of mRNA for CD3, TNF-α, IFN-γ, iNOS, IL-10 and arginase I increased up between the third and the fifth week after infection, decreasing thereafter." (PMID 23152844, 2012). "However, by days 5 and 7 post infection, there were increased numbers of inflammatory foci observed in IL-10−/− livers as compared to WT." (PMID 22880122, 2012).
infection (continued). "Interestingly, upregulation of IL10 resulting in the subsequent suppression of host innate immune responses to infection has been proposed as a mechanism which enables enhanced mycobacterial intracellular proliferation." (PMID 22384131, 2012). "In this malarial model, all the pro-inflammatory cytokines, TNFα, IFNγ, IL-1, IL-6 and IL-18 and the anti-inflammatory cytokine IL-10, were significantly elevated in the plasma throughout the infection with the highest level recorded during the late critical stage." (PMID 23323093, 2012). "In addition, IL-10 deficient mice mount heightened CD4+ and CD8+ T cell responses during the chronic/latent stage infection and harbor reduced levels of viral DNA load in infected mucosal (lungs) and non-mucosal (spleen) organs as compared with wild type mice." (PMID 23012619, 2012). "Additionally, we observed that ClpV contributes to IL-1β, IL-6, IL-10, and IL-17 production in murine macrophages in vitro, and using natural host infection, confirmed that changes in IL-17 and IL-6 production in vivo are ClpV-dependent." (PMID 23071529, 2012). "Besides, experiments performed on activated PBMCs showed a significant dose-dependent increase in IL-10 release upon infection." (PMID 22359669, 2012). "Whether such high IL-10 concentrations are still beneficial for the onset of infection or rather trigger NK cell activity is however questionable." (PMID 22615564, 2012). "IL-10 also plays an important suppressive role during the early stages of infection." (PMID 21811511, 2012). "By day 9 post infection, the number of foci in IL-10−/− livers was nearly comparable to WT." (PMID 22880122, 2012). "Moreover, low levels of IL-10 in lungs at day 1 correlated to mortality at days 2 (r = −0.77; p<0.05) and 3 of infection (r = −0.72, p<0.01)." (PMID 22347396, 2012). "Infection of MΦ and DCs with live mycobacteria is generally associated with induction of a strong pro-inflammatory phenotype with production of TNF, IL-12 and IL-6 that in turn is accompanied by the regulatory response, including secretion of IL-10." (PMID 22880012, 2012). "However, NK cell numbers were higher in IL-10−/− livers than in WT livers at 5 and 7 days post infection." (PMID 22880122, 2012). "IL-10 has been described as having anti-inflammatory effects during infection by inhibiting cytokine production and antigen presentation, however, more recently it was shown that IL-10 also limits recruitment of CD11b+ Ly6C+ monocytes following T. brucei infection." (PMID 23094119, 2012). "Whether this TNF/IL-10 imbalance results from an intrinsic incapacity of SMA patients to produce IL-10 or from an IL-10 unresponsiveness to infection is unknown." (PMID 22853732, 2012). "In this study, we also observed elevated IFN-γ (pg/ml, 24.97 l±24.00 in the patients versus 1.69±4.76 in healthy controls) and IL-10 (pg/ml, 10.75±6.93 versus 4.23±7.37) during the acute phase of infection although both cytokines returned to baseline levels during the convalescent phase." (PMID 22905277, 2012). "Furthermore, infection studies using IL10-/- mice have shown that IL-10 limits development of joint inflammation or IL10-/- mice are significantly better at clearing B. burgdoferi spirochetes at target tissue sites than are wild-type mice." (PMID 23024745, 2012). "Therefore, Lr1505 treatment would beneficially regulate the balance between pro-inflammatory mediators and IL-10, allowing an effective inflammatory response against infection and avoiding tissue damage." (PMID 22989047, 2012). "In addition, macrophages, which have been primed with Th1 cytokines (IFN-γ) and other proinflammatory cytokines (GM-CSF, TNF-α, etc.)generated by NK cells and macrophages, produce IL-10 during infections with mycobacterial organisms." (PMID 22666284, 2012).
infection (continued). "This can be explained by the fact that, although these genes are related to M2, IL-10 can be activated by the NF-κB signaling pathway in the late phases of infection to quell the immune response and arginase-1 is induced following toll like receptor stimulation." (PMID 22817641, 2012). "The ability of the strain MP287/03 to induce in MΦ some properties of the M2 cells, suggested that infection of the MΦ, pretreated with IL-10, by these bacteria may synergize in IL-10- dependent M2 polarization of these cells." (PMID 22863292, 2012). "Extensive studies have been showing that many intracellular pathogens that specifically target macrophages for infection could exploit IL-10 to suppress host innate and adaptive immune responses." (PMID 22909062, 2012). "Interestingly, RANTES, TNF-α and IL-10 levels were similar in all experimental groups by day 3 post infection." (PMID 23209745, 2012). "MRNA levels of genes encoding for chemokines (CXCL1 and CXCL5), cytokines (IL-10, IL-15 and IL-32), pattern recognition receptors (TLR1) and innate signaling molecules like IRAK3 and TRAF6, were all increased after MVA-C infection in comparison with MVA-WT-infected cells." (PMID 22536391, 2012). "The capacity for cDCs to drive polarization of IFNγ+IL-10+ cells may be as a result of their higher expression of IL-27 than CD11cint cells during infection." (PMID 22911108, 2012). "We suggest that IL-10 producing Tregs represent a fully activated stage of terminal differentiation with a limited life-span, which facilitates the return to immunological normality after clearance of an infection." (PMID 23226238, 2012). "On the other hand, increased IL-10 production may also be responsible for the increase in the number of parasites in the lymph nodes during the later phases of infection." (PMID 21390155, 2011). "Furthermore, infection with the mouse-adapted viruses, especially with MA-8 (p<0.01), induced higher levels of IL-10, G-CSF and moderate levels of MCP-1, but remarkably reduced levels of MIG in sera (P<0.05)." (PMID 22194944, 2011). "We tested this hypothesis by blocking IL-10 signaling with anti-IL-10 receptor blockade from week 6 (at the time of PZQ treatment) to week 8 (time of challenge infection)." (PMID 21829367, 2011). "Thus, neutralization of GAPDH, and hence blockade of the induced IL-10 production, allowed an effective immune response at an early stage of infection that prevented death of pups." (PMID 22114550, 2011). "However, we found that in both SHIV162p3 and SIVmac251 infected macaques, both Th-1 (IL-2, IFN-γ) and Th-2 (IL-4, IL-5, IL-6, IL-10, and IL-13) type cytokines were markedly elevated after infection." (PMID 21464951, 2011). "Interestingly, at 3 days after infection, the liver levels of IL-17, TGFβ, and IL-10 were significantly greater in BTBR mice than B6 mice (data not shown)." (PMID 21799730, 2011). "The main finding of this study is that IL-10 levels in NPAs at the time of hospitalization for severe RSV infection were highest in infants who developed physician diagnosed PBW in the year after infection." (PMID 21910858, 2011). "Elevated IL-10 was only detected at and after 5 days post infection." (PMID 22054060, 2011). "Concomitantly, treatment with rSAGs 4, 5 and 12 suppressed the expression of IL-12 and IFN-γ and elevated that of IL-10, suggesting that during infection these molecules may specifically impair the development of cellular mediated immunity." (PMID 21980402, 2011). "Contrary to BCG, on extending the time of evaluation to 16 weeks post-infection, rBCG vaccination resulted in a considerable decline in the levels of IFNγ and IL10; a significant increment in the levels of IL12 (p<0.05), while the levels of TNFα and TGFβ remained unaltered." (PMID 21533158, 2011).
infection (continued). "To assess whether a similar correlation exists in chicken embryo infection, we determined K60, IL-8, IL-1β and IL-10 transcription in the CAM of embryos infected with C. albicans deletion mutants in comparison to their parental strain." (PMID 21603634, 2011). "Using IL-10 deficient mice, we observed the absence of this cytokine resulted in a similar or increased lung and liver fungal growth at day 30 post-infection when compared with WT controls also exposed to CFA." (PMID 21731741, 2011). "In a model system infecting IL-10−/− mice with H. felis, depletion of neutrophils suppressed the Th1 immune response to infection, which suggests that granulocytes may also be involved in signaling the adaptive immune response." (PMID 22194986, 2011). "Post-hoc comparisons showed significantly elevated production of GM-CSF (P = 0.005), IL-2 (P = 0.008), and IL-5 (P = 0.03) in the chronic infection compared to uninfected groups and elevated production of IL-5 (P = 0.03) and IL-10 (P = 0.0008) in the chronic versus light infection groups." (PMID 21666788, 2011). "For example, the East Asian/Beijing strains induced significantly less pulmonary IL-10 on days 14 and 28 of infection than the other strains, which may enhance on-going immune-pathology and dissemination." (PMID 21931620, 2011). "IL-10 is a major anti-inflammatory protein that plays an essential role in regulating the balance between pathogen clearance by the immune response and immune mediated injury resulting from the immune response to pathogen infection." (PMID 21829368, 2011). "This is balanced with a modest secretion of IL-10 following scSIV-LMP1 infection of DC." (PMID 21592361, 2011). "Depending on the nature of the pathogenic stimulus, many cell types including neutrophils, NK cells, macrophages, dendritic cells (DC), regulatory and effector T cells have been shown to be capable of producing IL-10 both in vitro and in vivo in response to infection." (PMID 21829368, 2011). "IL-10 is a potent immunoregulatory cytokine that might be beneficial in the course of infection by attenuating the excessive host inflammatory response induced by up-regulated pro-inflammatory cytokines." (PMID 22046952, 2011). "Similarly, Leenstra and colleagues found that elevated IL-10 predicted a decrease in time to re-infection with several reports describing inverse correlations between IL-10 and S. mansoni or S. haematobium infection intensity." (PMID 21829367, 2011). "For 6 of the cytokines measured [IL-1a, IL-5, IL-10, IL-12(p40) and IL-12(p70)], the concentration in the supernatant dropped to a level which was below the detection limits for the particular assays by 15 min post H37Rv-infection." (PMID 22039457, 2011). "Infection of DCs from each donor (n = 3) with H37Ra consistently stimulated the release of pro- and anti-inflammatory cytokines including TNFα, IL-6, IL-8, IL-10, IL-1β and a modest increase in secretion of IL-12p70." (PMID 22024399, 2011). "Thus it appears that for some cytokines the booster effect of rHBHA upon BCG priming depends on the route of infection (i.n. for IL-12, IL-10; aerosol and i.n. for IFN-γ)." (PMID 21647410, 2011). "Continuous probiotic administration before and after infection decreased significantly (p < 0.01) the IL-10 release by the Peyer's patches mononuclear cells compared to the other infected groups, and the values were similar to those obtained from cells of the untreated control (C)." (PMID 21813005, 2011). "Therefore, each fraction at 50 μg/mL was tested for their inhibitory effects on BCG (MOI = 1, MOI: multiplicity of infection) induced IL-10 production in PBMac." (PMID 21447195, 2011). "Therefore, during the later phases of infection, IL-10 production increased in lymph node cultures from mice infected with both isolates, mainly in LTCP393(R)-inoculated animals." (PMID 21390155, 2011).